IL1B (interleukin 1 beta)
Diseases named in the same sentence as IL1B in open-access papers (continued):
Sharing a sentence is not in itself a finding about the gene and the disease.
gastric atrophy (23 papers, 2008 to 2024). "Th1 cells promote the expression of the cytokine IL-1β, which increases the risk of hypogastric acid, gastric atrophy, and gastric adenocarcinoma." (PMID 37138564, 2023). "In H. pylori-infected individuals, increased IL-1β expression due to polymorphisms in IL-1β significantly increases the risk of hypochlorhydria, gastric atrophy, and gastric adenocarcinoma." (PMID 35683528, 2022). "IL-1B-511 (rs 16944) has been associated with various inflammatory and infectious disorders, including H. pylori infection, chronic atrophic gastritis, gastric ulcer, and gastric carcinoma." (PMID 32382299, 2020). "In concurrence, lymphocyte-deficient mice expressing IL-1β in the stomach exhibited atrophic gastritis, metaplasia and dysplasia, which supports an independent role of IL-1β in gastric carcinogenesis." (PMID 32230726, 2020). "In fact, H. pylori-colonized individuals with high-expression polymorphisms in the IL-1β gene cluster, that is, IL-1β and its naturally occurring IL-1 receptor antagonist (IL-1RN), have increased risk for hypochlorhydria, gastric atrophy, and distal GC." (PMID 31662748, 2019). "A previous study has shown that increased expression of TNFα and IL-1β heightens the risk for atrophic gastritis and gastric adenocarcinoma in the early stages of H. pylori infection." (PMID 27006947, 2016). "Proinflammatory genotypes of the IL-1B gene, through its induction of gastric atrophy and gastric acid inhibition, increase the risk of gastric atrophy." (PMID 26401131, 2015). "Carriers of these pro-inflammatory polymorphisms revealed an increased IL1B gene expression pattern in the mucosa and increased prevalence of intestinal metaplasia and atrophic gastritis." (PMID 18842150, 2008). "Therefore, we tried to clarify whether COX‐21195, IL‐1β 511, and mPGES‐1 genotypes, which have been reported to be associated with gastric cancer, were also associated with gastric atrophy determined by AI." (PMID 36262541, 2022). "CLDN18 knockout mice show prompted onset of atrophic gastritis by disrupted proton barrier with IL-1β upregulation." (PMID 31040910, 2019). "Third, a recent study suggested that IL-1β suppresses Sonic Hedgehog (Shh) gene expression in parietal cells by inhibiting acid secretion and the release of cellular calcium, followed by gastric atrophy." (PMID 24216700, 2013). "Helicobacter pylori infection induces IL-1β production, and consequent hypochlorydria favours further colonization by pH-sensitive Helicobacter pylori, leading to the development of atrophic gastritis and adenocarcinoma." (PMID 19506726, 2008). "The severity of gastric atrophy may be influenced by the inhibition of the SHH signaling pathway by IL-1β, which may inhibit gastric-acid secretion and intracellular calcium release." (PMID 37687125, 2023). "The IL‐1β 511 TT genotype was also not significantly (P = 0.850) associated with the degree of gastric atrophy determined by AI." (PMID 36262541, 2022). "But, we tentatively draw the conclusion that H. pylori may lead to gastric atrophy via enhancing IL-1β mRNA expression, and IL-1β mRNA overexpression in gastric mucosa may be one of the generality characteristics for H. pylori-negative subjects with DHSS." (PMID 32382299, 2020). "H. pylori may lead to gastric atrophy via enhancing IL-1β mRNA expression, and IL-1β mRNA overexpression in gastric mucosa may be one of the generality characteristics for H. pylori-negative subjects with syndrome of dampness-heat in the spleen and stomach." (PMID 32382299, 2020). "The results showed that IL-1β mRNA was overexpressed in H. pylori-induced gastric atrophy." (PMID 32382299, 2020). "Previously, in a study assessing the effects of maximal gp130/STAT3 activation on the gastric mucosa, we reported that systemically administered IL-11 (20μg/day) caused gastric atrophy and mucus metaplasia through STAT3 activation, and coincident with elevated IL-1β expression." (PMID 25528766, 2015).
gastric atrophy (continued). "Thus, we speculate that H. pylori may induce gastric atrophy by IL-1β overexpression." (PMID 32382299, 2020). "In this study, we compared the determination of gastric atrophy by AI with atrophy diagnosed by expert endoscopists using the modified Kyoto classification, the histological OLGA classification, and the COX‐21195, IL‐1β 511, and mPGES‐1 genotypes." (PMID 36262541, 2022). "It has been demonstrated that IL-1β overexpression can directly induce gastric atrophy and dysplasia both in presence or absence of Helicobacter pylori infection." (PMID 19506726, 2008).
oral mucositis (23 papers, 2013 to 2025). Inflammation of the mucous membranes of any of the structures in the mouth. "However, if the opposite occurs, such as an increase in IL-1β, it will worsen the condition in patients, causing oral mucositis." (PMID 38978754, 2024). "Both Il1a and Illb transcripts were upregulated in the Il17ra−/− HNI + OPC mice compared to WT and may account for the increased neutrophil influx in the tongue tissue, which is similar to the role of IL-1α and IL-1β at the peak of damage during oral mucositis caused by HNI-only in Il17ra−/− mice." (PMID 35628751, 2022). "For example, in 5-fluorouracil (5FU)-induced oral mucositis in hamsters, AuNPs improved inflammation parameters, and decreased expression of genes encoding TGF-β, TNF-α, COX-2, IL-1β, NF-κB, and SMAD 2/3." (PMID 38082190, 2024). "Cytokines such as interleukin (IL)-1 beta (IL-1β), IL-6, IL-8, and tumor necrosis factor (TNF) have been linked to oral mucositis, and possibly xerostomia, during RT, manifested by elevated levels in saliva immediately after treatment in HNC patients." (PMID 36350483, 2022). "The pro-inflammatory cytokines increased significantly in the animals with untreated oral mucositis (5-FU) compared to the PVP group: IL-1β (p < 0.001 vs. 5-FU) and TNF-α (p < 0.0001 vs. 5-FU)." (PMID 32230975, 2020). "The primary damage of oral mucositis response describes an activation of transcription factors such as NF-κB leading to the production of pro-inflammatory cytokines such as TNF-α, IL-1β, and IL-6, which cause damage to both epithelium and connective tissue." (PMID 30274314, 2018). "Early inflammation, as indicated by the expression of the inflammatory markers TNFα, NF-κB, and IL-1β, is an essential component of early radiogenic oral mucositis." (PMID 28258409, 2017). "We recently defined the crucial role of ASC/caspase-1 activation and consequent IL-1β production in the establishment of inflammatory responses in irradiation-induced oral mucositis in rats." (PMID 28403142, 2017). "The initiation phase of oral mucositis starts with the damage by reactive oxygen species; then, NF-kB, TNF-α, IL-1β, and IL-6 carry the inflammation phase; immune cells cause the apoptosis of the epithelium and lead to the ulceration phase; eventually, the healing phase occurs." (PMID 37504247, 2023). "In contrast to IL-6 and IL-1β, anti-inflammatory effects in response to radiation exposure were reported for GM-CSF, and a local and systemic administration of GM-CSF showed a potential benefit in the treatment of oral mucositis." (PMID 37384298, 2023). "Management of oral mucositis may include usage of benzydamine mouthwash due to its anti-inflammatory properties, which inhibit production of TNFα and IL-1β." (PMID 32260309, 2020). "Interestingly, amifostine prevented the immunoexpression of key inflammatory markers, such as TNF-α, IL-1β, and iNOS, confirming the anti-inflammatory effect of that drug and suggesting the potential applicability to manage oral mucositis." (PMID 30810625, 2019). "Consistently, the animals that received 5-FU followed by mechanical trauma of the cheek presented macroscopic and microscopic lesions accompanied by an inflammatory response with accumulation of TNF-α, IL-1β, iNOS, and reduced salivary rate, indicating the establishment of ongoing oral mucositis." (PMID 30810625, 2019). "In an oral mucositis experimental model, administration of AZIL dramatically lowered TNF-α and IL-1β levels while boosting the levels of the anti-inflammatory cytokine IL-10." (PMID 37908315, 2023). "TNF-α can modulate the expression of other cytokines such as IL-1β and IL-6 and affect the apoptosis and survival of other cells, hence it was postulated that TNF-α was important in the pathogenesis of oral mucositis." (PMID 36499758, 2022). "The proinflammatory cytokines, IL-1β and TNF-α, play an important role in the pathophysiology of oral mucositis." (PMID 32230975, 2020).
oral mucositis (continued). "A study using an animal model of oral mucositis demonstrated that Atorvastatin significantly reduced TNF-α and IL-1β levels." (PMID 24130702, 2013). "Melatonin mitigates oral mucositis primarily by inhibiting NF-κB activation, thereby reducing pro-inflammatory cytokine expression (e.g., TNF-α, IL-1β) while also scavenging reactive oxygen species and enhancing antioxidant enzyme activity to protect and repair mucosal tissues." (PMID 40671993, 2025). "In contrast, we did not observe any significant differences in IL-1β levels or expression in cheek pouch tissue between groups subjected to 5-FU-induced oral mucositis." (PMID 25478918, 2014).
psychosis (23 papers, 2013 to 2025). "In this context, examining the interleukins (IL-1β, IL-2, IL-6, IL-10) in these patients offers a promising path toward understanding the early immunological disturbances associated with psychosis." (PMID 41008291, 2025). "The findings of this study provide preliminary insights into immune dysfunction in the early phase of psychosis and suggest that certain cytokines, particularly IL-2 and IL-1β, may have potential diagnostic relevance." (PMID 41008291, 2025). "The increased concentration of IL-1β h was found in first-episode psychosis (FEP) and in acutely relapsed (AR) patients and was normalized due to antipsychotic treatment." (PMID 40364201, 2025). "During the first episode of psychosis, increased concentrations of pro-inflammatory cytokines (IL-1β, IL-6, TNF-α) and elevations of TGFβ and IFN-γ are reported." (PMID 40364201, 2025). "Latest investigations reported high levels of TNF-α and IL-1β in patients with the first episode of psychosis and those taking antipsychotic agents; however, IL1-β levels decreased after remission." (PMID 37644489, 2023). "Studies showed that serum levels of TNF-α and IL-1β were high in chronic patients receiving antipsychotics; nevertheless, they were low in patients with the first-episode of psychosis." (PMID 37644489, 2023). "Other potential trait markers would be elevations of the pro-inflammatory cytokines IL-1β and TNF-α, but there is insufficient evidence of their rise in high- or ultra-high-risk states of psychosis." (PMID 36830990, 2023). "To date, only few studies have investigated cytokine levels in subjects with first-episode psychosis, reporting higher serum or plasma levels of IL-1β, IL-6, IL-12, INF-γ, TNF- α, TGF- β and soluble IL-2 receptor." (PMID 22749891, 2013). "The elevated IL-1β levels in our study can be interpreted in light of modern hypotheses linking inflammation to dysfunctions in neurotransmitter systems in psychosis." (PMID 41008291, 2025). "This study further illuminates the immunological profile of patients experiencing a first episode of psychosis, showing that IL-1β, IL-2, and IL-10 are not only significantly altered compared to the healthy controls, but are also associated with specific dimensions of the clinical picture." (PMID 41008291, 2025). "Three studies in the systematic review investigated the pro-inflammatory cytokine IL-1β but lacked comparison groups without psychosis/psychosis-risk with quantitative means for meta-analysis." (PMID 38141839, 2024). "Model 2, where non-CNS dysfunction emerges as a consequence of psychosis, is supported by meta-analytic evidence that resolution of acute psychosis is associated with normalization of previously elevated cytokines (IL-1β, IL-6, and TGF-β)." (PMID 29743584, 2019). "The authors suggested that IL-1β, IL-2, and IL-6 could serve as markers for psychosis, while TNF-α, IL-17, and IFN-γ were still elevated after antipsychotic treatment." (PMID 30766494, 2018). "Existing meta-analyses have suggested that patients with psychosis may exhibit an imbalance between pro-inflammatory cytokines (e.g., IL-1β, IL-6) and anti-inflammatory cytokines (e.g., IL-10), which could underlie immune dysregulation in the early stages of the illness." (PMID 41008291, 2025). "To investigate if IL-1β induced KYNA increases contribute to psychosis-like phenotypes in Grk3−/− mice, we investigated PPI following administration of IL-1β ICV (0.5 ng) in wildtype mice." (PMID 33976392, 2021). "In first-episode psychosis, interferon-γ (IFN-γ), IL-1RA, IL-1β, IL-6, IL-8, IL-10, IL-12, sIL-2R, TGF-β, and TNF were all significantly increased, and levels of IL-4 were significantly decreased." (PMID 32256401, 2020). "High levels of IL-1β correlated with the severity of the depressive and negative symptom dimensions at first-episode psychosis." (PMID 41010622, 2025).
psychosis (continued). "In our study, significantly higher concentrations of IL-1β were recorded in the patients with FEDN compared to the healthy controls, which aligns with numerous previous findings indicating a pronounced pro-inflammatory profile in the early stages of psychosis." (PMID 41008291, 2025). "Similarly, the positive correlation between IL-1β and KYNA levels in the FEP group, at both baseline and follow-up measurements, most likely denotes an immune-mediated upregulation of KP in early psychosis." (PMID 38987245, 2024). "In patients with psychotic disorders, the most frequent psychiatric manifestation in DGS, Th-17, Th-1 and Th-2 cells are increased with consequent elevation of proinflammatory cytokine IL-6 and IL1β." (PMID 36835652, 2023). "Gene expression analyses conducted only in those cytokines that were different in the serum (IL-1α, IL-1β, IL-6, IL-8 and TNF-α) revealed significantly increased mRNA levels of IL-1α (d = 0.6), IL-6 (d = 0.7) and TNF-α (d = 1.6) in first-episode psychosis patients when compared with controls." (PMID 22749891, 2013). "An updated review in 2019 reported increasing levels of IL-6, TNF-α, and IL-1β in different groups of patients, including first-time psychosis without medication and patients with first-time psychosis who were often treated with antipsychotics and chronic patients and patients with acute recurrence." (PMID 37644489, 2023). "The results of the ROC analysis in our study showed that IL-2, IL-1β, and IL-10 had significant discriminatory ability in distinguishing the patients with FEDN psychosis from the healthy controls, while IL-6 did not demonstrate a statistically significant value." (PMID 41008291, 2025).
respiratory failure (23 papers, 2015 to 2025). The significant impairment of gas exchange within the lungs resulting in hypoxia, hypercarbia, or both, to the extent that organ tissue perfusion is severely compromised. "ARDS, which was by far the main cause of respiratory failure in the study population, is characterized by persistent elevation in local and systemic levels of cytokines (namely IL-1β, TNF-α, IL-6, and IL-8), which contribute to the progression of lung injury and to extrapulmonary organ dysfunction." (PMID 35995816, 2022). "Since we found that hypothermia inhibited two-hit-induced acute respiratory failure with reduced IL-1β in the airways, we next evaluated the ability of bone marrow-derived macrophages (BMDMs) to release IL-1β under hypothermia." (PMID 40553503, 2025). "The recent COVID-19 pandemic is also associated with respiratory failure from ARDS and is the leading cause of mortality, accompanied by hyperinflammation, increased level of IL-1β and IL-6 in these patients." (PMID 33806560, 2021). "The rapidly progressive nature of respiratory failure corresponds with a cytokine storm, including IL1β, IL6, IL8, TNFα, detected in broncho-alveolar lavage fluids." (PMID 33362557, 2020). "Taken together, these data demonstrated that hypothermia could be a therapeutic strategy to modulate both IL-1β release and NETs formation for preventing the development of severe acute respiratory failure." (PMID 40553503, 2025). "Evidence suggests that inflammasome activation and interleukin-1β (IL-1β) release aggravate pulmonary injury and induce hypercoagulability, favoring progression to respiratory failure and widespread thrombosis eventually leading to multiorgan failure and death." (PMID 36209522, 2022). "However, there is controversy if excessive IL-6 synthesis is true a cornerstone of the pathogenesis of respiratory failure in Covid-19 or is just an epiphenomenon of increased IL-1β and TNFα in the cytokine storm." (PMID 33781216, 2021). "PRRSV infection induces the expression and release of a large number of inflammatory factors (such as IL-1β, IL-6, IL-8, TNF-α, etc.), leading to acute inflammation in the lungs, ultimately leading to respiratory failure and death." (PMID 36552462, 2022). "Thus, hypothermia is an important modulating factor in the NLRP3 inflammasome activation, IL-1β release and NETs formation, preventing LPS-HVV-induced acute respiratory failure." (PMID 40236184, 2025). "Such IL-1β, IL-18, and IL-33 were common inflammatory factors, our study showed that all of these could be increased during P-ALI, and even leading to respiratory failure." (PMID 38826806, 2024). "Besides expression of pro-inflammatory cytokines, such as IL-1β and TNF-α, the expression of chemokines CCL2, CCL3, CCL20, CXCL1, CXCL3, CXCL10, IL-8 was shown likely to contribute to clinical observation of excessive inflammatory tissue damage, lung injury, and respiratory failure." (PMID 33362782, 2020).